STAT1 (signal transducer and activator of transcription 1)
Diseases named in the same sentence as STAT1 in open-access papers (continued):
Sharing a sentence is not in itself a finding about the gene and the disease.
infection (continued). "In this study, the expression of T-bet and IFN-γ1 showed a significant increase, and subsequently STAT-1 expression was up-regulated at 1 day post-infection with NNVand immuno-stimulation with KLH, whereas slight increases in IL-13 and GATA-3 expression were noted at 3 days post-NNV infection." (PMID 33467734, 2021). "However, p-Stat1 expression was greatly enhanced in both MΦ subtypes, which was consistent with an increased production of IFNs following infection with RV." (PMID 34975859, 2021). "However, infection of STAT1 knockout clonal cell line with JCPyV in the presence or absence of IFNα suppresses viral replication indicating that IFNα exerts its anti-JCPyV activity via an independent STAT1 induction or activation." (PMID 34696366, 2021). "At the transcriptome level, the high expression levels of viral sensors MDA5 (IFIH1), R1G-1 (DDX58), and ISGS (ISG15, Mx1, Mx2, RSAD2, IFIT3, and IFIT5) and transcription factors like IRF-7 and STAT-1 that induce ISG expression were found in lymphocytes during virulent PPRV infection." (PMID 34631844, 2021). "Infection with both KUNV (a WNV variant) and NY99 strain of WNV prevents the translocation of STAT1 and STAT2 from the cytoplasm to the nucleus by inhibiting the STAT1 and STAT2 phosphorylation in response to IFN treatment, and it is also able to downregulate STAT1 expression." (PMID 34338586, 2021). "Reports show IFNγ inhibits GM-CSF, and experimental evidence in mice model shows primary DENV infection is IFNγ-dependent and STAT1-independent, which might be the reason for increased IFNγ and low GM-CSF during primary infection." (PMID 34447698, 2021). "We observed that these STAT1−/− fibroblasts do not demonstrate high levels of cytopathic effects after infection like other cell types that are highly susceptible to ZIKV, such as A549 and HAP1 cells." (PMID 34834920, 2021). "In addition to the high susceptibility of STAT1-/- mouse macrophages to HSV-1 infection, they are also highly sensitive to infection by other microbial pathogens and viruses." (PMID 34653236, 2021). "However, more studies are needed to detail the role and involvement of STAT1 in infection and transformation processes." (PMID 33076315, 2020). "We noted weaker slicing of the vsiRNA target by the pan-Ago IP from Stat1/2−/− mice than from Rag1−/− mice in response to NoVΔB2 infection (compare lanes 3 and 5), which appeared to correlate with the lower levels of vsiRNAs induced by NoVΔB2 in Stat1/2−/− mice than in Rag1−/− mice." (PMID 32753500, 2020). "Our work showed that miR-200b-3p, whose target might be Stat1 mRNA, was downregulated after infection with FM1, but was upregulated after XDY treatment." (PMID 32957919, 2020). "Notably, RAG1 KO mice exhibited a remarkable, STAT1-dependent capacity to control LCMV infection initially but this was ineffective as infection progressed." (PMID 32310998, 2020). "In addition, infection of primary MDMs with L.m. induced the phosphorylation of STAT1 on Tyr701at 6 and 24 h post infection." (PMID 33178195, 2020). "Importantly, mutations in STAT1 gene exist in humans; patients carrying either loss or gain of function (GOF) STAT1 mutations are susceptible to infections including ear infections." (PMID 32991625, 2020). "Stat1 was induced in both infection models but more prominently by bacteria." (PMID 32444775, 2020). "All Cd300lf+/+Stat1-/- succumbed to lethal infection by five dpi." (PMID 32251490, 2020). "Furthermore, Mφ of previously infected mice had increased expression of Stat1 and Cxcl9 1 and 5 days after (re-)infection." (PMID 32639232, 2020). "Notably, the numbers of Ly6Chi monocytes, F4/80hi CD11blo macrophages, eosinophils and mature neutrophils in STAT1/RAG1 DKO mice were significantly greater than in STAT1 KO mice following infection." (PMID 32310998, 2020).
infection (continued). "Moreover, we observed no obvious differences in Ago2-mediated RNA slicing by the endogenous miRNA-RISC isolated from Rag1−/− or Stat1/2−/− mice after either mock or NoVΔB2 infection." (PMID 32753500, 2020). "CNS expression of STAT1 protein was increased in response to infection by all three viruses." (PMID 32047134, 2020). "Notably, the transcription of JAK1 and STAT1 was enhanced both in the acute and the slow infection models." (PMID 32664675, 2020). "Therefore, we suggest that the abrogation of STATs activity by HBx to attenuate the interferon-mediated suppression of infection depends on STAT1 instead of STAT3." (PMID 32878239, 2020). "Northern blot analysis showed that infection with either NoVΔB2 or NoVmB2 induced production of vsiRNAs in Stat1/2−/− adult mice at levels comparable to that in C57BL/6 mice, which accumulated markedly reduced levels of vsiRNAs compared to that in Rag1−/− mice." (PMID 32753500, 2020). "However, no obvious differences were observed in the slicing of the miR-22 target by the pan-Ago IP from either Rag1−/− or Stat1/2−/− mice after mock or NoVΔB2 infection (compare lanes 7 to 9)." (PMID 32753500, 2020). "In ML29 infected STAT1-/- mice, the symptoms started to improve at the late stage of the infection." (PMID 30650607, 2019). "Finally, it has also been reported that STAT1 regulates the secretion of IL-4 by basophils upon infection with hRSV." (PMID 30936869, 2019). "In addition, our data reveal that PHLPP is also involved in the modulation of STAT1, which is critical for the activation of innate leukocytes in response to pathogen infections." (PMID 31555304, 2019). "At the same time, the level of p-STAT1 changed slightly from 12–48 h after infection with TGEV." (PMID 31781061, 2019). "In wild-type mice, ML29 and ML29P50 infection induced slightly lower T-cell responses Notably, in wild-type and STAT-1-/- mice infected either with ML29 or with ML29P50, similar levels of IFN-ɣ-secreting cells were induced after stimulation with GPC cocktails derived from LASV or MOPV." (PMID 30650607, 2019). "Thus, not only is STAT1 signaling in macrophages required for parasite control, but it is also necessary for this infection-driven dysbiosis." (PMID 31138751, 2019). "Interestingly, Stat1-/-Gsdmd-/- mice phenocopied the statistically significant survival advantage of Stat1-/-Nlrp3-/- mice upon gastrointestinal MNV infection when compared to Stat1-/- mice." (PMID 31017981, 2019). "Moreover, these analyses revealed that MLN from MNV-infected Stat1-/-Nlrp3+/- mice also displayed Nlrp3-dependent GSDMD cleavage after MNV infection, indicative of pyroptosis." (PMID 31017981, 2019). "The STAT1 protein abundance was indeed specifically reduced after 48 h with SFTSV infection." (PMID 31191546, 2019). "We observed that Ly6C+CD11b+ conventional DCs (cDCs) as well as PDCA1+CD11b+ pDCs were significantly induced in Stat1-/- and Ifnar-/- mice in frequencies after infection compared to uninfected Stat1-/- mice, while the DCs were similar between all uninfected mice." (PMID 29668683, 2018). "In our model, differential STAT1 expression at both phases of infection could be a possible point of synergy between type I and type II IFNs." (PMID 29324751, 2018). "Therefore, it appears that expression of pro-inflammatory cytokines and chemokines promoted by IFN-independent monophosphorylation of STAT1 comprise an alternative explanation for the cytokine storm observed during HP-PRRSV infection." (PMID 29662014, 2018). "However, studies in STAT1-deficient mice demonstrated early activation of CD4+ and CD8+ T cells, although these cells were depleted from the spleen by day 3 post-infection (PI) and mice succumbed prior to detectable antibody responses." (PMID 30416710, 2018). "However, macrophages from STAT1Y701F mice exhibited a modest gain-of-function in antibacterial immunity in comparison with Stat1−/− mice upon infection with intracellular microbe Listeria monocytogenes." (PMID 29662014, 2018).
infection (continued). "It was shown that during H37Rv infection, M1-type markers, phosphorylated STAT1 and iNOS, and M2-type markers, phosphorylated STAT6 and Arg-1, were increased in varying degree, indicating that M. tb infection induced both M1- and M2-type polarization of macrophages." (PMID 28835201, 2017). "Moreover, our experiments demonstrated that infection with CSFV strongly stimulated the downstream of STAT1 signaling in vitro and in vivo." (PMID 29312239, 2017). "The phosphorylation of STAT1 was first detected in control siRNA-transfected cells within 2 h of infection and peaked at 12 h of infection, then subsided at 24 h of infection almost to the level of 2 h; potentially due to the antagonism by IAV or caspase-mediated cleavage of total STAT1." (PMID 28769891, 2017). "Spleens sand pancreatic lymph nodes were removed on day 5 post-infection at the time when inflammation is detectable in the spleen and pancreatic lymph nodes, and the expression level of transcripts for STAT-1, the p40 subunit of IL-12 and IL-23 and IFN-γ was assessed by quantitative RT-PCR." (PMID 28301545, 2017). "While we were also able to detect HCV RNA—presumably from the residual inoculum—4 h following infection of STAT1−/− mice with cell culture-produced mtHCV (5 × 106 TCID50/mouse, intravenously), none of the animals were consistently viremic at any of the later time points." (PMID 27834208, 2016). "Phospho-STAT1 proteins were undetectable after infection, except at 2 hpi in A549 cells." (PMID 26859759, 2016). "In a previous work, we reported that live M. avium infection in macrophages kept the Jak/Stat-1 pathway active for a considerable period (more than 7 days), subsequent to the establishment of an intracellular infection and bacteria replication in the phagosome." (PMID 27437406, 2016). "Total levels of STAT1 expression increased at later time points post-infection in both genotypes." (PMID 27178303, 2016). "During early infection (within 24 h in cell culture), the virus blocks the phosphorylation and nuclear translocation of STAT1; however, during late infection, the virus modulates the IFN-1 response by inducing the downregulation of JAK1 and Tyk2 protein expression." (PMID 27367734, 2016). "However, significant IL6-dependent STAT1 Y701 phosphorylation was only observed with the wild-type and revertant but not the mutant virus at both early (24 h) and late times (72 h) post infection." (PMID 27387064, 2016). "IFN-α-induced phospho-STAT1 expression were largely reduced in NDV-infected A549 cells (designated IFNα+/infection+) at 2 hpi and were undetectable after 4 hpi; while the STAT1 in uninfected cells was phosphorylated (designated IFNα+/infection-) after stimulation with IFN-α." (PMID 26859759, 2016). "Thus, similarly to the effects in dendritic cells, infection of astrocytes with T. gondii results in the phosphorylation of STAT1 and the presence of IFN-γ (before or after infection) enhances these events." (PMID 27834206, 2016). "Moreover, compared to the rHep-Flury infection group, the phosphorylation level of STAT1 in Hep-dG-infected cells was significantly increased." (PMID 26217322, 2015). "Moreover, LV-shDUSP1 infection enhances translocation of STAT1 protein from the cytoplasm into the nucleus relative to in LV-cont-infected cells." (PMID 25798824, 2015). "Stat1-deficient mice kept under specific pathogen-free conditions do not succumb to infection and can be studied." (PMID 24489749, 2014). "To assess the role of STAT1 transcription factor in IFNγ-dependent protection against infection by T. cruzi, we first performed invasion assays using trypomastigotes in HFF cells expressing endogenous STAT1 and in STAT1-negative U3A cells, both in the absence and presence of IFNγ." (PMID 25340519, 2014).
infection (continued). "Similarly, expression of several genes in the canonical IFN signaling pathway, including Ifng, Jak2, Stat1, Stat2, Socs1, Irf1, Irf9, Tap1, Ifitm1, Psmb8, Ifi35, Gas1 and Fit3 were up-regulated during infection by the mutant strain." (PMID 25201772, 2014). "As different viruses antagonize IFNAR function by targeting distinct steps in the downstream signaling pathway including Jak1, Tyk2, Stat1, and Stat2 phosphorylation, this model of infection and inflammation may be relevant in the context of other infections." (PMID 24743949, 2014). "Furthermore, although experimental infection of immunocompetent and Stat1−/− mice was subclinical, histopathology revealed a progressive, subclinical multifocal hepatitis." (PMID 24225497, 2014). "However, it should be noted that 35 genes associated with inflammatory responses, notably STAT-1 (important for signaling through type I, II or III interferons), IL-5, and CD40L were upregulated following YFV-DakH1279 infection." (PMID 25412185, 2014). "Interestingly, at early time point post infection, activation of STAT1 signaling promoted expression of OAS-2 and Mx1." (PMID 24391501, 2014). "In our study we confirm that, even in the absence of any exogenous IFNγ added to the cells, infection with the highly pathogenic Y strain of T. cruzi results in a robust increase in the amount of cellular STAT1." (PMID 25340519, 2014). "Furthermore, Baron and Davignon described impaired STAT1 tyrosine phosphorylation in response to IFNγ in the 12 to 24 hour time period after infection with HCMV." (PMID 24699362, 2014). "Together, the infection experiments in two cultured human cell lines demonstrated that IFNγ is engaged in the protection from T. cruzi infection and, moreover, point to a role of STAT1 in this process." (PMID 25340519, 2014). "However, at a later time point (5 h after infection), the inhibition of PKR caused a significant decrease in STAT-1 serine 727 phosphorylation in all the cell lines, including the B27g- and B27H9F-transfected cells." (PMID 23349666, 2013). "However, even though the secretion of IFNβ was barely detectable 2 h post-infection/transfection, this was sufficient to induce near maximal phosphorylation of STAT1 at Tyr-701 (panel P4)." (PMID 23846693, 2013). "We sought to further characterize inhibition of STAT1 signaling in infected murine dendritic cells (DC) because this cell type has not previously been examined, yet is known to serve as an early target of in vivo infection." (PMID 23527309, 2013). "We next asked whether the increasing amount of phosphorylated STAT1 over time occurred through secretion of a soluble DC factor in response to infection." (PMID 23527309, 2013). "Since the decrease in cell apoptosis resulting from either Stat1 or Ifnar1 ablation was highly similar, the additional protection of LckCreStat1flfl mice from Lm infection is not due to a lesser rate of infection-induced apoptosis in Stat1-deficient T cells." (PMID 22719255, 2012). "In this study, we observed that although A/tree sparrow/Henan/1/04(H5N1) infection caused rapid IFN-β production and STAT-1 phosphorylation during the early stage of infection, it only induced low level endogenous RIG-I expression in comparison to H1N1 in A549 cells." (PMID 22862800, 2012). "Looking next at STAT1 serine phosphorylation, we found that infection with any of the Toxoplasma strains that we tested induced the serine phosphorylation of STAT1 slightly, but none of these strains strongly inhibited IFNγ induced serine phosphorylation of STAT1." (PMID 23240025, 2012). "To determine the degree to which cell type-specific Stat1 signaling determines this local immune response, we first analyzed the local chemokine/cytokine milieu in the peritoneal cavity over the course of the first three days of infection." (PMID 22719255, 2012). "The exacerbation of infection by Stat1 in T lymphocytes is particularly intriguing." (PMID 22719255, 2012).
infection (continued). "Importantly, and consistent with the actions of NO and JAK3/STAT1 signals in the modulation of sPLA2 expression, infection of the cells with STAT1 siRNA attenuated LPS-induced permeability mainly through the activation of sPLA2." (PMID 22788969, 2012). "We observed that IFNγ-induced STAT1 phosphorylation was blocked similarly by both isolates at all times post infection, whereas IFNα-induced STAT1/2 phosphorylation was dependent the degree of growth of the virus, the block developing more slowly in cells infected with the slower-growing GV isolate." (PMID 22163042, 2011). "However, deletion of B19R led to phosphorylation of STAT-1, even in the virus with K1L and C7L restored, compared to infection with the viruses containing B19R." (PMID 22096477, 2011). "Interestingly, our data also shows lower levels of STAT1 in infected cells, as it was detected down-regulated during infection in two fractions (fr." (PMID 21933386, 2011). "Additionally, we observed an initial 3.6-fold reduced STAT1 expression early after infection (6 h p.i.), while expression was up to 2-fold increased after 24 h and 48 h." (PMID 21629653, 2011). "In the first 72 hours of infection, the single-deficient mice lacking STAT1 or STAT2 possessed 50–100 fold higher levels of viral RNA than wild type mice in the serum, spleen, and other visceral tissues, but remained resistant to DENV-induced death." (PMID 21379341, 2011). "Brucella-infected wild type BMDM showed an increased in STAT1 tyrosine 701 at 6 hrs post-infection." (PMID 21829705, 2011). "Typically, one might expect to observe a restoration of virulence after infection of STAT1-/- mice with a virus that lacks an interferon antagonist, in this case VF1." (PMID 22174679, 2011). "Ubiquitination of TBK1 seemed an efficient tactic to activate IFN response because the endogenous TBK1 was K63-linked poly-ubiquitinated at 8 h post Sendai virus (SeV) infection and accompanied with phosphorylation of IRF3 and STAT1, the indications of the IFN production." (PMID 21364999, 2011). "In contrast, lungs of STAT1−/− mice showed significant viral RNA signal throughout the lungs, including prominent distribution into the periphery of the lung at early and late times post-infection." (PMID 20386712, 2010). "In contrast, STAT1−/− mice die within 1 week after infection with the parasite." (PMID 21217818, 2010). "Consistent with STAT1 and STAT2 activation, they also observed an increased abundance of genes encoding downstream targets of interferon signalling in response to infection, including the interferon regulatory factor 1 gene, located in the 5q31q33 chromosomal region." (PMID 20657648, 2010). "However, in STAT1 −/− mice, significant increases in protein expression patterns were detected across different time points, peaking between 9 and 15 days post-infection." (PMID 20386712, 2010). "Interestingly, mouse microarray data showed Jak2, Stat1 and Stat3 as vital proteins in this pathway and were up-regulated at the 4 days post-infection." (PMID 21172007, 2010). "Our results suggest a role of acidic pH in the control of intracellular Leishmania growth early during infection and identify for the first time an unexpected role of Stat1 in natural anti-microbial resistance independent from its function as IFNγ-induced signal transducer." (PMID 19381261, 2009). "Following infection of cells in an IFN-induced antiviral state, viral nucleocapsid proteins are initially localized within small cytoplasmic bodies, and appearance of these cytoplasmic bodies correlates with the loss of STAT1 from infected cells." (PMID 19458173, 2009). "HIV-1 infection also increased total STAT1 at 5 and 7 days after infection." (PMID 19404407, 2009). "Groups of Stat1-deficient mice and SV129 isogenic controls, or susceptible BALB/c mice, were inoculated with 106 infective L. major promastigotes, and the ability to resolve the infection was assessed during 12 weeks post-infection." (PMID 19381261, 2009).